DLEU1 (deleted in lymphocytic leukemia 1)
Description:
May act as a tumor suppressor.
Synonyms: LEU1; XTP6; NCRNA00021; LINC00021; BCMS1; BCMS; DLB1; DLEU7-AS1
Gene: Long non-coding RNA gene on chromosome 13 (50,081,725 to 50,906,856, forward strand). Ensembl gene ENSG00000176124.
Diseases named in the same sentence as DLEU1 in open-access papers:
DLEU1 is named in the same sentence as 52 diseases in open-access papers, as found by Europe PMC text mining. Sharing a sentence is not in itself a finding about the gene and the disease. The quoted sentences say what the papers report.
gastric cancer (12 papers, 2018 to 2026). A primary or metastatic malignant neoplasm involving the stomach. "Moreover, the up-regulated DLEU1 was shown to be associated with the survival of gastric cancer by promoting proliferation of gastric cancer cells." (PMID 30662454, 2018). "Long non-coding RNA (lncRNA) DLEU1 has been implicated in tumorigenesis, yet its mechanistic role in gastric cancer (GC) remains elusive." (PMID 41484982, 2026). "In gastric cancer, long non-coding RNA deleted in lymphocytic leukemia 1 (DLEU1) binds to SMYD2 and translocates to the apolipoprotein C1 (APOC1) gene promoter." (PMID 39482529, 2024). "Among these picked lncRNAs, DLEU1 has been corroborated to be elevated in multifold tumors (liver cancer, pancreatic ductal adenocarcinoma, colorectal cancer, and gastric cancer)." (PMID 35864972, 2022). "DLEU1 contributes to cell proliferation by recruiting LSD1 to epigenetically suppress KLF2 in gastric cancer." (PMID 35619131, 2022). "DLEU1 is upregulated in several cancers, including non-small cell lung cancer, gastric cancer, clear cell renal cell carcinoma, glioma, bladder cancer, hepatocellular carcinoma, breast cancer, colorectal cancer, ovarian cancer and cervical cancer." (PMID 32910787, 2020). "To determine whether DLEU1 regulates the expression of key mismatch repair (MMR) genes, we performed RT–qPCR analyses in AGS and MGC803 gastric cancer cell lines following DLEU1 overexpression." (PMID 41484982, 2026). "In addition, the upregulation of lncRNA DLEU1 was also associated with lymphatic metastasis and TNM stage of gastric cancer patients." (PMID 37781524, 2023). "Furthermore, lncRNA DLEU1 can promote gastric cancer cell proliferation by upregulating KLF2 by recruiting LSD1 to the KLF2 promoter region." (PMID 37781524, 2023). "DLEU1 has been shown to exhibit crucial carcinogenic roles in multiple tumors, including hepatocellular carcinoma, pancreatic ductal adenocarcinoma, colorectal cancer, and gastric cancer 11-14." (PMID 35864972, 2022). "For instance, DLEU1 expression was upregulated and promoted tumor proliferation and invasion by sponging miR‐133a in hepatocellular carcinoma 11; DLEU1 predicted awful survival of gastric cancer and contributed to tumor growth." (PMID 35864972, 2022). "Previous studies revealed that DLEU1 could promote progression of ovarian carcinoma and gastric cancer, while Balas and Johnson (2018)." (PMID 30662454, 2018).
colorectal cancer (11 papers, 2018 to 2024). A primary or metastatic malignant neoplasm that affects the colon or rectum. "For example, upregulated DLEU1 was observably correlated with neural invasion and poor differentiation in pancreatic ductal adenocarcinoma 12; DLEU1 overexpression promoted tumor cell invasion and growth in colorectal cancer." (PMID 35864972, 2022). "DLEU1 recruits SMARCA1 to epigenetically activate the KPNA3 gene in colorectal cancer, thereby promoting cell proliferation and migration." (PMID 35619131, 2022). "In contrast, DLEU1 expression is elevated in colorectal cancer and head and neck squamous cell carcinoma, contributing to tumor progression." (PMID 35619131, 2022). "For instance, DLEU1 is upregulated in colorectal cancer (CRC) and recruits SMARCA1 to epigenetically activate a downstream target gene, KPNA3, which leads to CRC progression." (PMID 34650128, 2021). "For instance, DLEU1 expression was correlated with the survival time of colorectal cancer patients." (PMID 33442418, 2021). "In terms of mechanism, we found that DLEU1 co-localized with SMARCA1 in colorectal cancer cells." (PMID 30098595, 2018). "Summarily, DLEU1 was up-regulated in colorectal cancer and may serve as a biomarker for CRC prognosis." (PMID 30098595, 2018). "Nevertheless, the roles of DLEU1 in other tumors including colorectal cancer remain elusive." (PMID 30098595, 2018). "The lncRNA lymphocytic leukemia 1 (DLEU1), targeting miR-320b/PRPS1, promotes the proliferation, migration, and invasion and reduces the apoptosis of colorectal cancer." (PMID 36203561, 2022). "Collectively, DLEU1 recruited SMARCA1 to epigenetically activate downstream gene KPNA3, thereby promoting proliferation and migration in colorectal cancer." (PMID 30098595, 2018). "In colorectal cancer tissues, by activating KPNA3 via recruiting SMARCA1, an essential subunit of the NURF chromatin remodelling complex, increased expression of DLEU1 was observed, and higher expression of DLEU1 in patients indicated lower survival rate and a poorer prognosis." (PMID 32742772, 2020).
breast carcinoma (10 papers, 2017 to 2023). "LncRNAs such as lymphocytic leukemia 1 (DLEU1) are associated with breast cancer and up-regulate CKAP2 expression to promote breast cancer malignancy via serving as a co-activator of HIF-1α." (PMID 36597032, 2023). "Considering the up-regulated DLEU1 in breast cancer, we applied the loss-of-function strategy in one TNBC cell line, MDA-MB-468, and one non-TNBC cell line, MCF7." (PMID 35853854, 2022). "Together, the data demonstrate the elevated expression of DLEU1 in breast cancer and its association with tumors of higher malignancy, supporting its potential involvement in the pathogenesis of breast cancer." (PMID 35853854, 2022). "Here we explored the malignant behaviors and underlying mechanisms regulated by DLEU1 in breast cancer." (PMID 35853854, 2022). "DLEU1 has been identified as an up-regulated lncRNA in breast cancer tissues and cells, particularly in tumors with high malignancy." (PMID 38012271, 2023). "We found that DLEU1 expression was significantly up-regulated in primary breast cancers (n = 1097), when compared to normal breast tissues (n = 114)." (PMID 35853854, 2022). "When stratifying breast cancer tissues into different molecular subtypes, we found that DLEU1 expression was significantly higher in triple-negative breast cancer (TNBC) tissues (n = 116) than in luminal (n = 566) or HER2-positive cancers (n = 37)." (PMID 35853854, 2022). "On the molecular level, we detected the significant increases of CKAP2 protein and mRNA expression in DLEU1-overexpressing MCF7 cells, supporting the association between DLEU1-induced up-regulation of CKAP2 and the enhanced malignancy of breast cancer cells." (PMID 35853854, 2022). "We demonstrated that up-regulation of DLEU1 was detected in breast cancer tissues and cells, particularly in tumors of higher malignancy." (PMID 35853854, 2022). "This study not only corroborates the oncogenic roles of DLEU1, HIF-1α, and CKAP2, but also justifies the potential of targeting these molecules in the treatment of breast cancers, particularly those associated with higher malignancy and worse prognosis." (PMID 35853854, 2022). "We first compared DLEU1 expression between 60 pairs of breast cancer and para-tumor normal tissues and detected its robust up-regulation in cancer tissues." (PMID 35853854, 2022). "Earlier studies have suggested deleted in lymphocytic leukemia 1 (DLEU1), a long non-coding RNA, is a prognostic biomarker for breast cancer." (PMID 35853854, 2022). "In the metastasis model, we found that shDLEU1#2 MDA-MB-468 cells generated significantly lower number of pulmonary metastasis than shNC cells, indicating the potency of targeting DLEU1 in inhibiting in vivo tumorigenesis and metastasis of breast cancer." (PMID 35853854, 2022). "Although studies suggest the up-regulation of DLEU1 in breast cancer, limited information is available regarding its biological effects and molecular mechanisms, which, therefore, becomes a focus for this study." (PMID 35853854, 2022). "We found that CKAP2 expression presented a positive correlation with DLEU1 in breast cancer tissues (n = 1104), implying a potential regulation between these two molecules, which has not been reported." (PMID 35853854, 2022). "In breast cancer, three studies have reported the up-regulation of DLEU1 in cancer tissues, consistent with our findings from clinically acquired tissue samples or from database analysis." (PMID 35853854, 2022). "Lastly, we measured DLEU1 expression in a panel of breast cancer cell lines of different molecular subtypes, including luminal MCF7 and T47D, HER2-positive SK-BR-3, and TNBC MDA-MB-231, MDA-MB-436, and MDA-MB-468 cells." (PMID 35853854, 2022). "DLEU1 is obviously overexpressed in breast cancer and accelerates migration, invasion of breast cancer cells." (PMID 34113562, 2021).
breast carcinoma (continued). "In many cases, DLEU1 acted as an competing endogenous RNA (ceRNA) for a microRNA, such as miR-381 in cervical cancer, miR-99b in bladder cancer, miR-490 in endometrial cancer, miR-421 in glioma, miR-671-5p in osteosarcoma, and microRNA-300 in breast cancer." (PMID 35853854, 2022). "In vivo, depletion of DLEU1 inhibited xenograft growth and metastasis of breast cancer cells." (PMID 35853854, 2022). "DLEU1 knockdown inhibited the growth and the motility of breast cancer cells." (PMID 35853854, 2022). "In addition, DLEU1 deletion has been found in atypical spindle cell lipoma 13, and DLEU1 is highly expressed in breast cancer." (PMID 28598010, 2017). "MiR-19a and lncRNA DLEU1 might be co-expressed to regulate the expression of ER in breast cancer." (PMID 34220926, 2021). "In summary, here we present seminal findings that DLEU1, by activating HIF-1α-induced transcription of CKAP2, promotes malignant growth and metastatic spread of breast cancer." (PMID 35853854, 2022). "We demonstrated the direct interaction between DLEU1 and HIF-1α in breast cancer cells, the impact of knocking down each on the expression of CKAP2, and their separate yet positive correlation with CKAP2 level in breast cancer." (PMID 35853854, 2022). "When compared to the non-tumorigenic breast epithelial MCF10A cells, DLEU1 expression was elevated in all breast cancer cell lines examined but more strikingly in three TNBC cell lines." (PMID 35853854, 2022). "To test this hypothesis, we explored the interactions between DLEU1, HIF-1α, and CKAP2 in breast cancer tissues acquired from patients or database, in breast cancer cells cultured in vitro, and in in vivo xenografts or metastasis models." (PMID 35853854, 2022). "Therefore, DLEU1, by acting as a coactivator for HIF-1α, up-regulates CKAP2 expression and promotes malignancy of breast cancer." (PMID 35853854, 2022). "DLEU1 also promotes migration, invasion and EMT by breast cancer cells by targeting miR-30019." (PMID 34650128, 2021). "Targeting DLEU1, HIF-1α, or CKAP2 may thus benefit breast cancer treatment." (PMID 35853854, 2022). "DLEU1 is up‐regulated in MCF‐7 cells and might be coexpressed with miR‐19a to co‐regulate the expression of ER‐α (ESR1), which influences the occurrence and development of breast cancer." (PMID 28598010, 2017). "In contrast, we did not detect any correlation between DLEU1 and HIF-1α levels in breast cancer or the effect of shDLEU1 in altering HIF-1α expression, suggesting that their crosstalk is through physical interaction, but not expressional regulation." (PMID 35853854, 2022).
ovarian carcinoma (10 papers, 2017 to 2022). A malignant neoplasm originating from the surface ovarian epithelium. "miR-146b-5p cooperates with lncRNA DLEU1, a significant key in ovarian cancer development, consequently heightened DLEU1 expression and lowered miR-146b-5p expression in POF." (PMID 36564840, 2022). "It was observed that DLEU1 is under-expressed in ovarian cancer and regulates TFAP2A expression via miR-429, thereby suppressing tumorigenesis." (PMID 34740384, 2021). "To explore the role of DLEU1 in ovarian cancer, we examined its expression in normal ovary and ovarian cancer tissue samples, and found that DLEU1 expression was significantly higher in the ovarian cancer tissues than in the normal tissues." (PMID 28598010, 2017). "We predicted that miR-146b-5p may interact with lncRNA DLEU1, a crucial player in ovarian cancer, and explored the interaction between DLEU1 and miR-146b-5p." (PMID 34740384, 2021). "In addition, DLEU1 aggravates the progression of ovarian cancer through interacting with miR-490-3p to modulate CDK1 expression." (PMID 34113562, 2021). "However, increased DLEU1 expression has been shown to sequester the tumor suppressor function of miR-290-3p and increase growth and invasiveness of ovarian cancer cell lines in vitro." (PMID 30382883, 2018). "In summary, we believe that DLEU1 promotes the pathogenesis and development of epithelial ovarian cancer through its interaction with miR‐490‐3p, thereby altering the expression of the miR‐490‐3p target genes, that is, CDK1, CCND1 and SMARCD1, as well as the expression of MMP2, Bcl‐xLand P70S6K." (PMID 28598010, 2017). "We predicted that miR-146b-5p might interact with lncRNA DLEU1, a crucial player in ovarian cancer." (PMID 34740384, 2021). "Therefore, we believe that DLEU1 and miR‐490‐3p interact in ovarian cancer." (PMID 28598010, 2017).
chronic lymphocytic leukemia (9 papers, 2013 to 2026). "Relevant research indicates that DLEU1, as a protective predictor, is a candidate gene of tumor suppressor involved in B-cell chronic lymphocytic leukemia." (PMID 38264748, 2023). "The lncRNA deleted in lymphocytic leukemia 1 (DLEU1) is located at 13q14.3, a region recurrently deleted in chronic lymphocytic leukemia, and it is supposed to be a tumor suppressor gene in hematopoietic tumors." (PMID 35619131, 2022). "The two long non-coding RNA (lncRNA) genes DLEU1 and DLEU2 map to a critical region at chromosomal band 13q14.3 that is recurrently deleted in solid tumors and hematopoietic malignancies like chronic lymphocytic leukemia (CLL)." (PMID 23593011, 2013). "DLEU1 and DLEU2 (Deleted in lymphocytic Leukemia 1 and 2) are two lncRNAs produced from the 13q14.3 tumor suppressor locus which is deleted in lymphomas and hematopoitic cancers like Chronic Lymphocytic Leukemia (CLL)." (PMID 26082843, 2015). "Here we describe an example where two lncRNA genes (DLEU1 and DLEU2) are epigenetically deregulated together with a cluster of neighboring protein-coding tumor suppressor genes in almost all patients suffering from chronic lymphocytic leukemia." (PMID 23593011, 2013).
glioma (8 papers, 2020 to 2022). A benign or malignant brain and spinal cord tumor that arises from glial cells (astrocytes, oligodendrocytes, ependymal cells). "We proposed that DLEU1 can encode small peptides with ion channel activity, leading to an increase in glioma permeability, which in turn increases brain edema and even increases the risk of cancer cell development, invasion and metastasis." (PMID 33735310, 2021). "Based on RNA-seq data from TCGA, we demonstrated that the differential expression gene in glioma, named lncRNA deleted in lymphocytic leukemia 1 (lncRNA DLEU1), was dramatically associated with a poor prognosis." (PMID 33362537, 2020). "Knockdown of DLEU1 inhibits glioma progression and promotes temozolomide chemosensitivity by regulating autophagy." (PMID 35603200, 2022). "Recently, studies have revealed that DLEU1 plays critical roles in the pathologic progression of renal cell carcinoma, glioma, osteosarcoma, cervical cancer, and bladder cancer." (PMID 35647200, 2022). "Consistently, DLEU1 has been demonstrated to be dysregulated and exerts an oncogenic function in tumors such as oral squamous cell carcinoma, glioma, endometrial cancer, and non-small-cell lung cancer." (PMID 35619131, 2022). "Recent studies had demonstrated high-expressed lncRNA DLEU1 was significantly associated with advanced WHO grades, lower Karnofsky Performance Status (KPS) score, and proliferation of glioma cells." (PMID 33362537, 2020). "Additionally, we verified that lncRNA DLEU1 was high expressed in 108 gliomas, compared with 19 normal brain tissues." (PMID 33362537, 2020). "To further investigate whether lncRNA DLEU1 was involved in the progression of glioma, we evaluated the effect of lncRNA DLEU1 on glioma proliferation." (PMID 33362537, 2020). "Given that lncRNA DLEU1 expression was significantly up-regulated in glioma samples, a therapy targeting lncRNA DLEU1 could provide a prospective strategy for glioma treatment." (PMID 33362537, 2020). "Moreover, recent reports had demonstrated that knockdown of lncRNA DLEU1 significantly inhibited the invasion and migration abilities on osteosarcoma cells and glioma cells." (PMID 33362537, 2020). "In addition, knockdown of lncRNA DLEU1 suppressed glioma progression by inducing cell cycle arrest, and inhibited the invasion and migration by depressing EMT." (PMID 33362537, 2020). "However, very few reports showed the prognosis value and molecular functions of abnormal lncRNA DLEU1 expression in gliomas." (PMID 33362537, 2020). "In our study, the role of lncRNA DLEU1 in autophagy was first explored in glioma cells." (PMID 33362537, 2020). "The preceding results indicated that lncRNA DLEU1 could promote the migration and invasion of glioma cells, which meant lncRNA DLEU1 might be involved in progression of EMT, which plays a significant role in the infiltration and metastasis of tumors." (PMID 33362537, 2020). "Western blot analysis showed that knock down of lncRNA DLEU1 dramatically reduced the LC3II expression, transition from LC3I to LC3II, as well as the expression of p62 and ATG7, which suggested that lncRNA DLEU1 deletion could suppress autophagy in glioma cells." (PMID 33362537, 2020). "Furthermore, lncRNA DLEU1 deletion could promote TMZ sensitivity to glioma cells via enhancing apoptosis and regulating autophagy, which enriched the mechanism of temozolomide sensitivity and provided a potential biomarker for the individualized use of temozolomide in glioma." (PMID 33362537, 2020). "The high expression of DLEU1 and IT1 significantly reduces the survival rate of glioma patients." (PMID 33735310, 2021).
bladder cancer (7 papers, 2019 to 2022). "Previous studies had shown that lncRNA DLEU1 was associated with drug resistance in bladder cancer on cisplatin." (PMID 33362537, 2020). "DLEU1 promotes tumor progression and chemotherapy resistance in bladder cancer by regulating the miR-99b/HS3ST3B1 axis." (PMID 35619131, 2022). "Moreover, DLEU1 was shown to be overexpressed in bladder cancer specimens and overexpression of DLEU1 promoted cell invasion and growth and cisplatin resistance via modulating miR-99b expression." (PMID 35647200, 2022). "Recent evidence indicates that DLEU1 could promote cisplatin resistance in bladder cancer and nasopharyngeal carcinoma." (PMID 35619131, 2022). "Although accumulating evidence has shown the important function of long non-coding RNAs (lncRNAs) in tumor progression and chemotherapy resistance, the role of lncRNA DLEU1 in regulating proliferation, invasion, and chemoresistance of bladder cancer (BCA) cells remains largely unknown." (PMID 30984249, 2019).